LGR5 (leucine rich repeat containing G protein-coupled receptor 5)
Diseases named in the same sentence as LGR5 in open-access papers (continued):
Sharing a sentence is not in itself a finding about the gene and the disease.
cancer (continued). "CD44 and LGR5 are the target genes of WNT signaling pathway and mark CSCs and normal intestinal stem cells, suggesting that upregulation of WNT signaling pathways is important for both normal and cancer stem cells in the intestine." (PMID 29064439, 2017). "In addition, the levels of cancer stem cell markers, such as aldehyde dehydrogenase-1, cluster of differentiation 133 (CD133), CD44, Lgr5, Musashi-1, Ephrin receptor, and Bmi-1 increased after exposure to BP compounds." (PMID 28862656, 2017). "Lgr5 and its ligand, RSPO2, might have the same effect on enriching and maintaining ESCC cancer stem cells." (PMID 28404917, 2017). "Protein levels cancer stem-like biomarkers (CD133, ALDH1, Lgr5, E-cadherin, Vimentin, Snail1) were also tested, indicating that the expression of CD133, ALDH1, Lgr5, Vimentin and Snail1 in the 131I-AC133.1 mAb group were lower than the other groups, while the level of E-cadherin was higher." (PMID 28430648, 2017). "Our observations indicate that not all of Bmi1+ or Lgr5+ tumorigenic cells behave as cancer stem cells." (PMID 28176811, 2017). "Finally, we identified cell surface markers for cardiac progenitors, such as the Leucine-rich repeat-containing G-protein coupled receptor 4 (LGR4), belonging to the same subfamily of LGR5, and LGR6, established tissue/cancer stem cells markers." (PMID 26783251, 2016). "The expression of LGR5 was strikingly up-regulated in sphere cells but not in cancer tissues or parental adherent cells." (PMID 28033430, 2016). "To explore if LGR5 is associated with chemotherapy resistance in MGC803 cells, we conducted an MTT assay to evaluate the viability of LGR5-transfected and mock-transfected cells after treatment with oxaliplatin (L-OHP), a platinum-based antineoplastic agent used as chemotherapy in cancer clinics." (PMID 28033430, 2016). "Through unsupervised clustering in stage II cancers, we identified two cluster groups that are broadly defined by inflammatory or immune-related factors (CD3, CD8, COX-2 and FOXP3) and stem-like factors (CD44, LGR5, SOX2, OCT4)." (PMID 25906747, 2015). "As cancer cell survival can involve MEK/ERK and Akt signalling pathways, we assessed whether LGR5 knockdown had any effects on the activated (phosphorylated) forms of these kinases." (PMID 26517508, 2015). "Lgr5 expressing cells in hair follicles were recently shown to be targets of papillomavirus induced cancer but there is not a clear indication by these results as to how this is involved with benign versus locally aggressive tumors." (PMID 25474466, 2014). "Leucine-rich repeat-containing G-protein coupled receptor 5 (LGR5) is a seven transmembrane spanning receptor that has recently been identified as a somatic stem cell marker that plays key functional roles in both normal development and cancer." (PMID 23596566, 2013). "Lgr5 is a membrane protein related to G protein-coupled receptors (GPCR)s whose expression identifies stem cells in multiple tissues and is strongly correlated with cancer." (PMID 24386388, 2013). "LGR5 expression of the overall cohort was positive in 65 cases (51%) of all non-malignant tissues and 103 cases (81%) of all cancer tissues." (PMID 22530031, 2012). "An LGR5-immunoreactivity was found in all tissue components, i.e. stroma cells, endothelial cells, cells in the non-neoplastic epithelium and in cancer cells." (PMID 22530031, 2012). "LGR5-immunoreactivity in stroma cells was observed in 49 (39%) of all non-malignant tissues and in 80 cases (63%) of all cancer tissues." (PMID 22530031, 2012). "Interestingly, the expression of Lgr-5 was found to be expressed in freshly-isolated cancer cells, but not in Coala cancer cell line at later passage (P21)." (PMID 40758205, 2025).
cancer (continued). "The expression of PD-L1 on cancer cells can be directly upregulated by MACC1 itself, or through secondary factors such as HGF/c-MET, via activated STAT1/3, PI3K/Akt, or Wnt/β-catenin signaling, from metabolic alterations or by promoting cellular stemness via Oct4/NANOG/LGR5." (PMID 39580452, 2024). "Decreased expression of LGR5 at the site of fat invasion in the high HG and EMT phenotype groups may suggest that LGR5 affects the prognosis of DA, indicating that it may be related to cancer cell EMT." (PMID 35123536, 2022). "Interestingly, in some cases, we observed a remarkable increase in LGR5 expression in the myoepithelium of nonneoplastic ducts surrounded by cancer cells." (PMID 34493772, 2021). "Notably, LGR5 expression was completely restricted to the basal cells surrounding the DCIS, whereas no carcinoma cells expressed LGR5." (PMID 34493772, 2021). "In the following glucose-free phase, the total number of cells did not change, but the number of LGR5-positive cells was increased, suggesting that the population of cancer stem cells was increased by transfer of organoids from glucose-sufficient to glucose-depleted condition." (PMID 31835877, 2019). "To elucidate whether PKM2 loss in cancer cells is linked to the increase of CSC-like function, we next isolated EpCAM+Lgr5+ cells from polyps and cultured single Lgr5+ CSC without Wnt3a and R-spondin." (PMID 30996297, 2019). "However, studies have also shown that selective ablation of Lgr5+ CSCs using gene-specific approach is effective temporarily yet is eventually overcome by robust plasticity of non-targeted cancer cells." (PMID 31358061, 2019). "In addition, the LETM1 expression is correlated with cancer stemness-related gene LGR5 (p < 0.001) and HIF1α expression (p < 0.001), but not with others." (PMID 31500591, 2019). "The present data further confirmed that Lgr5 expression varied at different sites of CRC, which might be ascribed to the intrinsic heterogeneity of CRC and the differences in the invasiveness of cancer cells at different sites." (PMID 30046385, 2018). "To study LGR5+ cells in vivo, we initially used an LGR5‐EGFP expressing organoid (clone #1) that by exome sequencing revealed few acquired mutations compared to the parental population, none of which affected known cancer driver genes." (PMID 28468934, 2017). "According to our findings, LGR5 might promote HCC metastasis through inducting EMT process, and thus could be used as a candidate biomarker for prognosis as well as a target for the cancer therapy." (PMID 28881613, 2017). "On one hand, metaplastic Paneth cells may support the nascent Lgr5+ cancer stem cell analogous their role as niche of normal CBCs." (PMID 22745693, 2012). "Lgr5 expression was significantly higher in carcinoma than in normal mucosa (P=0.001)." (PMID 23153436, 2012). "Here, the authors suggest that the variations in malignant phenotypes between LGR5-positive cancer stem cells and LGR5-negative cells could be due to their distinct mechanical phenotypes observed in vitro, determined by the membrane to cortex attachment proteins Ezrin/Radixin/Moesin." (PMID 38637494, 2024). "In addition, the investigation of the relationship between immune CYT and Lgr5+ cells, as well as the exploration of the TME to see how the increase and/or decrease in the levels of immune cytolytic activty affect the population of Lgr5+ cells, is crucial in metastasis and cancer treatment." (PMID 38612436, 2024). "Indeed, LGR5+ and TROY+ cells may give rise to cancer stem cells." (PMID 36672658, 2023). "In fact, based on the hypothesis that ISCs Lgr5 + are cells at the origin of CRC, and that multiple metabolic pathways for ISCs function during homeostasis and tumorigenesis have been identified, many features of stem cells metabolism are similar to the “ cancer stem cells” observed in cancer." (PMID 33691728, 2021).
cancer (continued). "To determine whether physciosporin affects the expression of cancer stemness markers in CRC cells, we monitored the protein expression level of aldehyde dehydrogenase-1 (ALDH1), cluster of differentiation 133 (CD133), CD44, Lgr5, and Musashi-1 (Msi-1) in CSC221 cells." (PMID 31795147, 2019). "CBX8 has been shown to induce cancer stemness and chemoresistance in CRC through activation of the transcription of LGR5 in a noncanonical manner." (PMID 35681547, 2022). "These carcinomas expressed tdTomato, confirming their allograft origin, and characterized by predominant CD44 expression and absence of Lgr5 expression." (PMID 31901081, 2020). "Of note, YAP knockdown led to a decrease in the size and number (by 2-fold) of spheres and cancer stem cell markers ALDH1A3, CD133 and Lgr5, with no change in CD44." (PMID 27527859, 2016). "Since, unlike LGR5-GFP, the OSCAR reporter does not rely on any cell type-specific promoter or activity, but instead reports low CDK9 activity it is likely to be generically useful for imaging and isolation of dormant cells in many tissue or cancer types." (PMID 34083536, 2021). "The expression was not interrelated (i.e., between LGR5, FZD7, and MIST1) and may reflect the coexistence of different CSC phenotypes supporting the contention that cancers can harbor heterogeneous and biologically distinct populations of CSCs." (PMID 31827644, 2019).
infection (38 papers, 2014 to 2025). The state of being infected such as from the introduction of a foreign agent such as serum, vaccine, antigenic substance or organism. "Pathogenic infection of Lgr5+ ISCs attenuates Wnt signalling and impairs their ability to regenerate the injured epithelium, exacerbating tissue damage, delaying recovery, and predisposing to re-infection." (PMID 33673710, 2021). "Removing CD13+ cells didn’t affect the number of CD24+SSChigh and CD24+SSClow cells in CD13+-removed IPEC-J2 cells, even upon TGEV infection and rescued Lgr5 ISCs loss, which was induced by TGEV." (PMID 31959773, 2020). "We observed that infection with adenovirus encoding Cas9 and Lgr5 gRNA decreased the mRNA level of Lgr5 and the number of Lgr5+ cells in the intestine." (PMID 29079780, 2017). "We observed that infection with adenovirus encoding Cas9 and Lgr5 gRNA infection decreased the protein and mRNA levels of Lgr5 in the liver." (PMID 29079780, 2017). "Moreover, deletion of MHCII in LGR5+ cells prevented remodeling of the tissue upon infection with pathogenic Heligmosomoides polygyrus and induced an increase in LGR5+ cell numbers, which disrupted the mucosal immune response." (PMID 34095127, 2021). "Infection induced crypt cell necrosis, reduced villus height, decreased villus-to-crypt ratio, and lowered numbers of goblet cells and Lgr5+ intestinal stem cells." (PMID 41600671, 2025). "The lower mRNA levels of LGR5 in the NE-challenged groups during peak infection are likely a consequence of a deregulated intestinal renewal process." (PMID 40881634, 2025). "Constitutively active Wnt/β-catenin signaling because of Apc inactivation exacerbates H. pylori–induced Lgr5 expression and stemness, both of which persist even after eradication of the infection." (PMID 39191487, 2024). "Infection of Irgm1 knockdown lentivirus significantly upregulated the transcription of Wnt target genes (Lgr5 and Sox9) and Wnt luciferase activity in a dose-dependent manner." (PMID 35197566, 2022). "Since expression of Bmp ligands, which inhibit Lgr5 expression, is blocked upon infection, we wondered if the expression of antimicrobial genes is also inhibited by BMP signaling." (PMID 35332152, 2022). "We examined the effects of diets on Lgr5+ colonic stem cells in Lgr5CreERT2/Rosa26LacZ reporter (Lgr5-R) mice during CR infection." (PMID 35008767, 2021). "The crosstalk between immune cells and Lgr5+ ISCs also helps shape the small-intestinal niche post infection." (PMID 33673710, 2021). "Infection by TGEV disrupted the Notch signaling for Lgr5 ISCs self-renewal and differentiation via down-regulating DII4 and Hes5 protein expression both in in vivo and in vitro." (PMID 31959773, 2020). "In contrast, infection with Ad-RSPOs provoked crypt (hyper)proliferation and increased production of LGR5+ cells." (PMID 29316729, 2018). "(I) Western blot of Ascl2 and Lgr5 showing IL-17 antibody-abrogated C. rodentium-infection-induced colon stem cell marker expression." (PMID 30543324, 2018). "We next overexpressed miR-196a in LGR5- CRC cells by lentivirus mediated miR-196a infection (p-miR-196a)." (PMID 27880730, 2016). "By nature, the ISCs are particularly sensitive to injury under stressful conditions including infection; however, a quiescent cell population of secretory progenitor cells (+4 cells) can de-differentiate into bona fide LGR5+ rapidly dividing ISCs." (PMID 26820624, 2016). "Recent studies in mice have demonstrated that M cells are generated from Lgr5+ intestinal stem cells (ISCs), and that infection with Salmonella enterica serovar Typhimurium increases M cell formation." (PMID 26820624, 2016). "As LGR5 is required for efficient CM differentiation in hPSCs, we hypothesized that infection with a doxycycline (DOX)-inducible LGR5-expressing lentivirus might rescue the cardiac defects in GATA6-/- hESCs." (PMID 40080060, 2025).
infection (continued). "Intestinal epithelial cells, including Lgr5 + stem cells, Paneth cells, and others, play crucial roles in infection resistance by promoting post-injury repair, producing antimicrobial peptides and defense factors, and maintaining the stability of the intestinal environment." (PMID 40979361, 2025). "Apcmin/+ organoid cells expressed more Lgr5 at a steady state than their WT counterparts, and this could be further increased by infection." (PMID 39191487, 2024). "However, these BMP antagonists incompletely block BMP signaling as some pSMAD1/5/8 activation is still found in LGR5+ stem cells, and we observed a distinct increase of pSMAD2 in intestinal crypts upon infection with N. brasiliensis." (PMID 35559665, 2022). "With the discovery of MmuPV1, we were able to observe, in the context of a natural infection model for papillomavirus-induced pathogenesis, that Lgr5+ progenitor cells, which reside in the bulge of the hair follicle, contribute substantially to PV-associated SCCs in mouse skin." (PMID 36016373, 2022). "In contrast, by flow cytometry and immunofluorescence analyses of fresh “untouched” crypt samples for stem cells and TA cells, we found that loss of Il-22, epithelial Stat3, or Il-18 in mice indeed cause a reduction of Lgr5+ and Ki67+ crypts at the steady state and during AIEC infection." (PMID 35169117, 2022). "It has previously been reported that Salmonella and other intracellular pathogens preferentially invade mitotic and dividing cells; thus, Lgr5+ stem cells may be more prone to infection." (PMID 34710062, 2021). "Furthermore, experimental infection of mice revealed H. pylori dependent expansion of Lgr5+ gastric stem cells, with greater expansion occurring with CagA positive H. pylori, suggesting that translocation of CagA into stem cells stimulates their proliferation." (PMID 29049360, 2017). "Furthermore, we anticipate that our findings related to the role of Lgr5 will assist in defining molecular mechanisms of infection and dysfunction of the stem cell niche." (PMID 25214524, 2014). "The original Lgr5+ ISCs are lost or differentiated upon DSS, infection, and radiation, and the newly generated ISCs acquire a fate-like state due to activation of IFN-γ and YAP/TAZ." (PMID 39872442, 2024). "Infection with ST decreased the proliferation genes PCNA, Ki67, and Cyclin; the ISC marker gene Lgr5; the quiescent ISC marker gene Bmi1; the Goblet cell marker gene Muc2; the Paneth cell marker gene Lyz1; and Wnt3a mRNA levels (p < 0.05)." (PMID 38540864, 2024). "The induction of Lgr5 was fairly specific, as other gastric stem cell markers, such as Sox2, Troy, Runx1, Lrig1, and others were not induced as a consequence of infection; an exception was Ascl2, the expression of which mirrored that of Lgr5." (PMID 39191487, 2024). "Addition of β-ADP heptose alone was not sufficient to induce Lgr5, also not when combined with a ΔPAI mutant infection." (PMID 39191487, 2024). "Maintaining organoid cells in 2D for up to 48 h without infection or antibiotics was per se not sufficient to increase their Lgr5 expression." (PMID 39191487, 2024). "At Day 28 post injury, the Lgr5-mRNA level in the OE infected with Lenti-shLgr5-a was reduced by 48 ± 8% compared to infection with Lenti-shCtrl, while Lenti-shLgr5-b infection did not affect the Lgr5 expression level in the OE." (PMID 35966594, 2022). "The results showed that expression of the stem cell marker gene Lgr5 was not detectable 24 hours post-infection (hpi)." (PMID 32390999, 2020).
infection (continued). "Similarly, crypts were damaged upon RSPO signalling inhibition (upon infection with Ad-RNF43/ZNRF3-ECDs and Ad-LGR5-ECD); however, in this particular case the crypt formation was rescued by (simultaneous) Wnt signalling activation." (PMID 29316729, 2018). "The lack of significant change to LGR5 transcript levels at the peak of infection suggested that the crypt hyperplasia was not due to the expansion of ISC population." (PMID 28323899, 2017). "We observed that Ad-Lgr5 shRNA infection decreased the mRNA level of Lgr5, and there were no Lgr5+ cells induced by CCl4 when mice were treated with Ad-Lgr5 shRNA." (PMID 29079780, 2017). "Lgr5 expression increased in a multiplicity of infection (MOI)-dependent manner; as an MOI of 50 showed strong effects on Lgr5 expression without completely overgrowing the cells or causing cytotoxicity (and data not shown), this MOI was used throughout the study unless otherwise indicated." (PMID 39191487, 2024).